IL33 (interleukin 33)
Diseases named in the same sentence as IL33 in open-access papers (continued):
Sharing a sentence is not in itself a finding about the gene and the disease.
rheumatoid arthritis (continued). "The IL-33/ST2 system is involved in numerous diseases and pathological conditions, e.g., fibroproliferative and cardiovascular diseases, asthma, and rheumatoid arthritis (RA)." (PMID 22246057, 2012). "Recent evidence suggests a role for IL-33/ST2 in several rheumatological diseases, including rheumatoid arthritis (RA), osteoarthritis (OA), psoriatic arthritis (PsA) and systemic lupus erythematosus (SLE)." (PMID 21871091, 2011). "In rheumatoid arthritis synovial fibroblasts, calycosin significantly potentiated Nrf2 translocation by inducing p62 accumulation and Keap1 degradation to activate HO-1 and NQO1, thus suppressing IL-6 and IL-33 secretion and COX-2 mRNA and protein expression." (PMID 36358507, 2022). "Its expression in human rheumatoid arthritis patients determined the presence of a regulatory circuit consisting of HIF-1α and IL-33, leading to the preservation of disease pathogenesis and indicating that IL-33 expression is induced by hypoxia to maintain hypoxic gene activation." (PMID 35159396, 2022). "It is known that IL-33 and ST2 are expressed in the synovium of patients with rheumatoid arthritis." (PMID 35401921, 2022). "TNF-α significantly induced IL-33 mRNA expression and protein synthesis, and overexpression of IL-33 significantly increased TNF-α-induced IL-6, IL-8, and matrix metalloprotease (MMP)-3 in rheumatoid arthritis synovial fibroblast." (PMID 33490289, 2020). "In addition, increased levels of IL-33 are detected in patients with multiple sclerosis (MS), systemic lupus erythematous (SLE), type 1 diabetes (T1D) and rheumatoid arthritis (RA)." (PMID 30949175, 2019). "IL-33 may also be involved in rheumatoid arthritis (RA) pathogenesis." (PMID 27964756, 2016). "IL‐33 and ST2 concentrations were also found to be increased in sera and synovial fluid of rheumatoid arthritis (RA) patients." (PMID 33133598, 2020). "Studies showed that IL-33 played an important role in the pathogenesis of multiple autoimmune diseases, such as systemic lupus erythematosus (SLE), rheumatoid arthritis (RA) and inflammatory bowel disease (IBD)." (PMID 31572353, 2019). "Both, IL-33 and ST2 are expressed in the human and mouse model of rheumatoid arthritis (RA) synovial tissue, are elevated in the sera and synovial fluids of RA patients and manifest correlation with disease progression." (PMID 29867945, 2018). "Interestingly, in Th1/Th17-mediated EAE and rheumatoid arthritis, a protect role of IL-33 was observed in EAE through promoting AAM polarization and inhibiting Th1/Th17 differentiation, while IL-33 exhibit an adverse effect in rheumatoid arthritis via enhancing Th1/Th17 immune response." (PMID 28423665, 2017). "This study identifies IL-33 as a critical regulator/enhancer of TNF-α-induced functions in RA-SFs, pointing to a central role of this cytokine in the perpetuation of pro-inflammatory and pro-destructive processes in rheumatoid arthritis (RA) and other inflammatory and degenerative diseases." (PMID 22246057, 2012).
allergic asthma (100 papers, 2010 to 2026). A asthma with a basis in a pathological type I hypersensitivity reaction. "Increased reprogramming of FoxP3+ regulatory T cells (Tregs) in allergic asthma is associated with IL-33 production, exacerbating airway reactivity." (PMID 39301028, 2024). "After adjusting for age, sex and five viral categories, IL33 achieved nominal significance (p = 0.017) for a positive association with allergic asthma development." (PMID 36685501, 2022). "GM-CSF promotes type 2 immunity to allergen and increases the susceptibility to allergic asthma through the GM-CSF/IL-33/OX40L pathway." (PMID 33327561, 2020). "Interleukin receptor associated kinase M (IRAK-M) is a PIN1 target critical for IL-33 signaling in allergic asthma." (PMID 30886621, 2019). "Here we show that interleukin receptor associated kinase M (IRAK-M) is a PIN1 target critical for IL-33 signaling in allergic asthma." (PMID 29686383, 2018). "TG2-deficient mice showed reduced IL-33 expression following induction of allergic asthma compared to those in the WT control." (PMID 23496815, 2013). "TG2-deficient mice revealed decreased IL-33 expression following the induction of allergic asthma compared to that in the WT control." (PMID 23496815, 2013). "IL-33 has been linked to a number of inflammatory disorders including allergic asthma, rheumatoid arthritis, allergic rhinitis and ulcerative colitis." (PMID 23169007, 2013). "Similarly, comparison of IL-17RB-deficient and ST2-deficient mice in models of allergic asthma has shown that IL-33 induces expansion of IL-13-producing ILC2s more potently, correlating with airway constriction." (PMID 41409758, 2025). "IL-33 drives Th2-associated cytokine production in children and adults with allergic asthma." (PMID 37048784, 2023). "The importance of these alarmins in allergic asthma is demonstrated by a recent genome-wide association study (GWAS), which showed that genetic polymorphism in the gene encoding IL-33 or its receptor IL-1RL1 (ST-2) associates closely with the development of allergic asthma." (PMID 36466877, 2022). "In addition, single nucleotide polymorphisms (SNPs) in IL-33 have been associated with eosinophil counts, which is related to the pathogenesis of allergic asthma." (PMID 35432313, 2022). "Accumulating evidence also indicate that IL-33 is implicated in various form of allergic asthma." (PMID 27870920, 2016). "The results showed that the expression levels of TSLP, IL-33, IL-4, IL-5, and IL-13 were higher in clusterB or gene clusterB than those in clusterA or gene clusterA, which suggested that clusterB or gene clusterB is highly linked to allergic asthma characterized by the Th2 immune response." (PMID 33763115, 2021). "In the previous study, up-regulated IL-33 and ST2 expression in OVA-sensitized lungs are reduced through salidroside administration, reflecting that salidroside treats allergic asthma by repressing lung ILC2 activation via targeting the IL-33/ST2 axis." (PMID 38650035, 2024). "In allergic asthma, increased expression of alarmins like TSLP, IL-33, and IL-25 in the airway epithelium is associated with airway obstruction." (PMID 39301028, 2024). "It has been found that IL-33 is responsible for mediating the Th2-type immune response in an allergic asthma model." (PMID 39061526, 2024). "In experiments in vitro, the percentage of ILC2s in peripheral blood from patients with allergic asthma was significantly greater and responsive to IL-33 and IL-25, leading to the production of higher levels of IL-5 and IL-13 than healthy controls." (PMID 36674744, 2023). "It has been reported that the IL-33 levels in lung tissue and airway smooth muscle cells in allergic asthma patients are significantly higher than those in healthy donors." (PMID 36674744, 2023). "IL-33-neutralizing antibodies inhibit the production of TSLP in the airway in a murine model of ovalbumin (OVA)-induced allergic asthma." (PMID 36834541, 2023).
allergic asthma (continued). "Stressed, hyper-reactive, or damaged airways trigger the release of IL-33 which activates the innate lymphoid program to elicit an allergic asthma lung phenotype." (PMID 36506643, 2022). "IL-33 in allergic asthma act as an ‘alarm’ alerting the immune system after endothelial or epithelial cell damage." (PMID 35432313, 2022). "In clinical practice, serum IL-33 levels are positively correlated with the severity of allergic asthma, and IL-33 concentrations have been used to assess the severity of allergic asthma." (PMID 36291105, 2022). "In contrast to above reports, IL-33 induction of our murine HDM-induced model was less although our model possesses phenotype allergic asthma; eosinophilic inflammation, airway hyperreactivity and allergen-specific IgE production." (PMID 34162937, 2021). "Type 2 immune responses to allergen exposure play crucial roles in the pathogenesis of allergic asthma, which is initiated by epithelium-derived cytokines including IL-33, IL-25 and thymic stromal lymphopoietin (TSLP)." (PMID 33607992, 2021). "Recently, IL-33 has been reported to exert a biological role in the pathogenesis of human diseases; specifically, its critical role in allergic asthma has recently been confirmed." (PMID 33919784, 2021). "Taken together, our findings indicate that IL-4Rα–unresponsive FoxP3+ Tregs result in exaggerated innate Th2-type, IL-33–dependent airway inflammation and a break in tolerance during allergic asthma." (PMID 32931477, 2020). "Significant reduction in il-33 expression in PGT-treated MLE-12 cells under papain stimulation, suggest a role of PGT in regulating IL-33 production and in earlier stages of allergic asthma development." (PMID 33374657, 2020). "The S. aureus allergen serine protease-like protein D (SplD) induces allergic asthma in C57BL/6J mice through the IL-33/ST2 signaling axis." (PMID 33072128, 2020). "S. aureus can secrete a wide range of virulence factors, among which staphylococcal serine protease-like proteins (Spls) have been identified as bacterial allergens and inducers of allergic asthma in C57BL/6J mice by activating the IL-33/ST2 signaling axis." (PMID 33072128, 2020). "Antibody‐targeting IL‐33 has been proven successful in mouse disease models, with ameliorated symptoms of experimental allergic asthma." (PMID 32566227, 2020). "tTG-null mice displayed reduced IL-33 expression following induction of allergic asthma compared to those in the WT control, which was also found in tTG-/- mice and tTG inhibitor-treated mice in our study of Sj parasitism." (PMID 31200771, 2019). "Further supporting a role for ILC2s in allergic asthma, the frequency of ILC2s and the levels of IL-33 in the bronchoalveolar lavage (BAL) of patients with allergic asthma were positively correlated with severity of the disease." (PMID 31134050, 2019). "Data concerning the high serum levels of IL-33 and IL-31 levels were also gained from patients affected by the combination of allergic asthma and rhinitis." (PMID 31766607, 2019). "Taken together, our results show that dephosphorylated PTRF prevents allergic asthma exacerbations by limiting IL-33 release." (PMID 29977243, 2018). "In this study we provide evidence that IL-33 exacerbates antigen-driven features of allergic asthma and we propose that mast cells and ILC2s have a central role in driving these processes." (PMID 28652606, 2017). "ILC2s have been identified as important players in allergic asthma and their accumulation can be induced via IL-33 in response to allergens such as Alternaria and house dust mite, as well as influenza virus." (PMID 28652606, 2017). "In human studies of allergic asthma, IL-33 and ST2 expression in serum, lung tissue and BALF have found to be higher in asthmatics compared to healthy controls and correlate with asthma severity." (PMID 26762527, 2016).
allergic asthma (continued). "Similar to allergic asthma and CRS, atopic dermatitis has been associated with increased expression of TSLP, IL-25, and IL-33 in the skin." (PMID 26965110, 2016). "To examine the potential suitability of IL-33 as a target for vaccination against allergic asthma, we have developed a fusion protein vaccine against this cytokine." (PMID 26214807, 2015). "The present study aims to investigate the plasma levels of 25(OH) Vit D, IL-31, and IL-33 in children with allergic asthma and rhinitis." (PMID 25061262, 2014). "25-Hydroxyvitamin D [25(OH) Vit D], IL-31, and IL-33 plasma levels were measured in 28 controls (HC), 11 allergic rhinitis (AR) patients, and 35 allergic asthma with rhinitis (AAR) patients." (PMID 25061262, 2014). "By binding to its cognate receptor, T1/ST2, IL-33 initiates immune pathways such as the type-2 immune response in allergic asthma." (PMID 23169007, 2013). "The alveolar walls alone account for over 99% of the lung's internal surface area 32 and as such the type-2 pneumocytes are perfectly positioned for sensing allergens and secreting IL-33 to instigate the type-2 response in allergic asthma." (PMID 23169007, 2013). "We have generated a fluorescent reporter mouse line, Il33Cit/+, to define the expression profile of IL-33 in vivo and demonstrate its temporal and spatial expression during experimental allergic asthma responses." (PMID 23169007, 2013). "IL-33 is a strong inducer of the Th2 immune response, and its role in the immunopathogenesis of allergic asthma had been documented." (PMID 23496815, 2013). "Consistent with this, allergic asthma sufferers express higher levels of IL-33 and IL-25 than healthy subjects 7–10." (PMID 23169007, 2013). "Using experimental models of allergic asthma we describe the temporal and spatial expression profile of IL-33 in vivo during type-2 lung inflammatory responses." (PMID 23169007, 2013). "Secretion of IL33 by airway epithelial cells is a key phenomenon in allergic asthma." (PMID 41404114, 2025). "Furthermore, activated mast cells in allergic asthma release serine proteases (chymotrypsin and trypsin) that generate mature, active forms of IL-33, which can potentiate ILC2 activity." (PMID 39301028, 2024). "In individuals with concurrent allergic asthma and rhinitis, plasma IL-33 and IL-17 levels are elevated and positively correlated, suggesting the IL-33/ST2 axis might induce Th2 and Th17 immune responses in allergic airway diseases." (PMID 36834541, 2023). "By contrast, the IL-33/ST2 pathway is involved in non-allergic asthma." (PMID 38082335, 2023). "Indeed, it was shown that the relationship between IL-33 and ILC2s directly shapes the clinical symptoms of allergic asthma." (PMID 36466877, 2022). "In conclusion, our results suggests that estrogen can play a protective role in allergic asthma by negatively regulating IL-33 induced ILC2 and IL-5/IL-13 cytokine production, furthermore we demonstrated that this effect is regulated by NF-κB signaling pathway." (PMID 36506643, 2022). "Moreover, in vivo KIF2A transfection reduced IL-33 and autophagy in the lung, leading to the attenuation of allergic asthma." (PMID 35718777, 2022). "We constructed a cellular allergic asthma model using IL-33 induction." (PMID 36611831, 2022). "ILC2s can produce Th2 cytokines, which promote airway hyperresponsiveness and allergic asthma, but ILC2s also upregulate IL-33 expression in mice and humans, and depletion of these cells leads to failure of wound healing, suggesting they have a protective effect in this process." (PMID 33688303, 2021). "Furthermore, epithelial cell-derived cytokines such as IL-33 play a major role in the initiation of allergic asthma." (PMID 35386975, 2021). "ClusterB was highly linked to the Th2 immune response and had higher expression levels of TSLP, IL-33, IL-4, IL-5, and IL-13, which indicated that clusterB may be related to allergic asthma." (PMID 33763115, 2021).
allergic asthma (continued). "We recently reported that IL-23 was secreted from airway epithelial cells in a murine model of allergic asthma elicited by house dust mite allergen exposure and administration of IL-33, an epithelium-derived innate cytokine, following activation of IL-23R signaling." (PMID 31956268, 2020). "STING/TBK1/IRF3 axis and IL-33 signaling, required for cGAMP-induced allergic inflammation, may be novel therapeutic targets for allergic asthma." (PMID 31616416, 2019). "IL-33 has been extensively studied in allergic asthma and other allergic conditions." (PMID 29859068, 2018). "The gene that encodes for ST2 produces its transmembrane receptor but also produces a soluble form of ST2 (sST2), which acts as a binding decoy for IL-33 and thus down-modulates IL-33 activity during inflammatory responses, such as in experimental allergic asthma and collagen-induced arthritis." (PMID 30483263, 2018). "This point of view may have been triggered by the use of robust ILC2 induction models, such as administration of IL-25, IL-33, papain, and Alternaria to study these cells in the context of allergic asthma or dermatitis." (PMID 29250067, 2017). "Despite IL-33 and IL-25 being identified as important promoters of allergic inflammation in mouse models, the influence of these cytokines on the effector role of basophils in human allergic asthma needs to be further characterized." (PMID 26762527, 2016). "This study investigated the effect of IL-25 and IL-33 on basophils in a model of allergic asthma." (PMID 26762527, 2016). "There are numerous causes of this disorder, and recent evidence indicates that the alarmin cytokines IL-25 and IL-33 may play a key role in promoting allergic asthma." (PMID 26762527, 2016). "Our findings indicate that the alarmin cytokines IL-33 and IL-25 increase basophil activation and migratory potential, and may pose as a novel therapeutic targets for the treatment of allergic asthma." (PMID 26762527, 2016). "Interleukin-33 (IL-33) is an IL-1 family cytokine that signals via its receptor T1/ST2, and is a key regulator of inflammation, notably the type-2 response implicated in allergic asthma." (PMID 23169007, 2013). "Our study suggests that EOS might be the main source of IL-33 receptor among the airway inflammatory cells present after SBP-Ag, and EOS could contribute to IL-33-mediated effects in allergic asthma." (PMID 23844029, 2013). "Therefore, IL-33 targeting is a promising therapeutic strategy for allergic asthma." (PMID 34084159, 2021). "Furthermore, the suppression of IL-33 and induction of IL-37 could exert anti-inflammatory activity in allergic asthma." (PMID 33919784, 2021). "Our data showed the Lineage-cells from both mugwort-allergic asthma group and HDM-allergic asthma group could produce significant amounts of IL-5 and IL-13 after the stimulation with IL-33 when compared to IL-2 alone (all P < 0.05, respectively), or medium alone (all P < 0.05, respectively)." (PMID 29449864, 2018). "Once activated, for example by IL-33 or IL-22, ILC2 secrete IL-5 and IL-13, contributing to AHR and airway inflammation in OVA-induced allergic asthma." (PMID 40095032, 2025). "The role of IL-4, IL-5, IL-6, IL-33, TNF-α and IFN-γ in the pathogenesis of allergic asthma is well documented has been elaborately explicated elsewhere." (PMID 38807596, 2024). "The Th2 cytokines that play an important role in allergic asthma, like IL-5, IL-13, CCL17, and IL-33 along with total IgE in serum were measured." (PMID 32582180, 2020). "We therefore provide evidence for the indispensable role of IL-4Rα signaling in maintaining Treg stability and IL-4–responsive Tregs in limiting IL-33–derived ILC2-driven AHR and airway inflammation in HDM-induced allergic asthma." (PMID 32931477, 2020). "IL-33, a well-known DAMP (alarmin), is one of the key molecules for the pathogenesis of allergic asthma." (PMID 31616416, 2019).